EP300 (EP300 lysine acetyltransferase)
Diseases named in the same sentence as EP300 in open-access papers (continued):
Sharing a sentence is not in itself a finding about the gene and the disease.
lymphoma (31 papers, 2015 to 2025). A malignant (clonal) proliferation of B- lymphocytes or T- lymphocytes which involves the lymph nodes, bone marrow and/or extranodal sites. "Here, using EP300-mutated adult T-cell leukemia/lymphoma cells and an EP300-selective degrader, we reveal that EP300 loss leads to pronounced dysregulations in DNA replication dynamics and persistent genomic instability." (PMID 41354653, 2025). "Some of these events are specifically related to lymphomas, such as in case 5, which includes nine single-nucleotide events associated with lymphomas, e.g., the p.P925T missense variant in EP300 (COSV54337074), or events in MCL1 and PTPN13." (PMID 40404986, 2025). "EP300 mutations are also prevalent in follicular lymphoma, and it has been postulated that EP300-mutant lymphoma cells have an abnormal germinal center transcriptional regulation." (PMID 40666506, 2025). "The frequency and type of CREBBP/EP300 mutations vary significantly among lymphomas due to different geographic regions or subtypes." (PMID 36831561, 2023). "Epigenetic dysfunction, such as gain-of-function mutations of EZH2 and loss-of-function mutations of CREBP and EP300, disrupts the normal biological link between lymphoma cells and immune TME, and motivates immune evasion in GCB lymphoma." (PMID 35935878, 2022). "Mutations in EP300 have been frequently found in skin squamous cell carcinoma and various types of lymphomas." (PMID 33167967, 2020). "For example, CREBBP/EP300 gene mutations are frequently detected in diverse lymphomas, such as follicular lymphoma (FL), DLBCL, in situ follicular neoplasia, peripheral T-cell lymphoma (PTCL), angioimmunoblastic T-cell lymphoma (AITL), and plasmablastic lymphoma (PBL)." (PMID 36831561, 2023). "However, joint loss of Crebbp and Ep300 completely abolished GC formation, suggesting EP300-dependency in Crebbp-deficient lymphoma cells." (PMID 36831561, 2023). "Interestingly, CREBBP-mutated lymphoma B cells maintained this dependency toward EP300 enzymatic activity which identify a unique vulnerability that provide exciting opportunities of targeting single mutant CREBBP or EP300 GC-derived lymphomas." (PMID 34335584, 2021). "In lymphomas, inactivating mutations in CREBBP and EP300 facilitate effective immune evasion through impaired neoantigen presentation, including in combination with other chromatin remodeling factors." (PMID 41301688, 2025). "Germline EP300 mutations can cause autosomal dominant Rubinstein-Taybi syndrome (RSTS) and are associated with predisposition to lymphoma." (PMID 36686744, 2022). "We further observed differences in the IC50 values of A-485 in five lymphoma cell lines, indicating a potential correlation between CREBBP/EP300 deficiency and sensitivity to HAT inhibitors." (PMID 33911074, 2021). "Recent discoveries of the prevalence of inactivating mutations in the acetyltransferase genes EP300 and CREBBP in lymphomas have highlighted the crucial role of epigenetics in the pathobiology of lymphomas, including especially DLBCL." (PMID 25671298, 2015). "EP300 and CREBBP are both often mutated in squamous cell carcinoma and lymphomas." (PMID 37705968, 2023). "Mutation in this complex in lymphoma has been described, showing that about 39% of DLBCL and 41% of follicular lymphoma patients have genomic deletions and/or somatic mutations that inactivate or remove the acetyltransferase domain of EP300 and CREBBP." (PMID 28725161, 2017). "Comparing with historical control (NCT01852435), the 2-year PFS and OS rates of double-expressor lymphoma phenotype (DEL) were improved, and negative prognostic effect of histone acetyltransferases CREBBP/EP300 mutations was also mitigated by CR-CHOP." (PMID 33097085, 2020). "In our study, we included KMT2D, CREBBP, EZH2, EP300, MEF2B, and TET2 in our lymphoma panel." (PMID 31403034, 2019).
B-cell lymphoma (29 papers, 2012 to 2025). "CREBBP and EP300 mutations are one of the main pathogenic mechanisms of B cell non-Hodgkin lymphoma (B-NHL) and have a direct impact on the use of drugs targeting acetylation/deacetylation mechanisms." (PMID 37884941, 2023). "The synthetic lethal interaction between CREBBP and EP300 genes, two frequently mutated epigenetic modulators in B-cell lymphoma, was further validated in the previously published CRISPR-Cas9 screens and inhibitor assays." (PMID 33911074, 2021). "EP300 mutations were recently identified as a major pathogenetic mechanism shared by common forms of B-cell NHLs." (PMID 25364581, 2014). "Furthermore, we identify frequent pathogenic variants involving CREBBP and EP300, both of them associated with epigenetic abnormalities in GC-derived B-cell lymphomas such as cHL." (PMID 38473705, 2024). "Our results thus suggest that targeting the remaining HAT function may hold therapeutic potential for B-cell lymphomas with deficiency in either CREBBP or EP300." (PMID 33911074, 2021). "In consistence with experimental data showing that HDACIs can rescue deficits in histone acetylation induced by CREBBP/EP300 mutations in B-cell lymphoma, our results provided clinical evidence that tucidinostat may mitigate the negative prognostic impact of CREBBP/EP300 mutations on DLBCL." (PMID 33097085, 2020). "Examination of alterations in key pathways implicated in B-cell lymphomas suggests involvement in chromatin remodelling (CREBBP and EP300) and regulators of NF-κB signalling (TNFAIP3, BCL10, MYD88, CD79B and CARD11) were affected." (PMID 39460552, 2024). "Inactivating mutation of EP300 frequently occurs in DLBCL and FL, the two most common B-cell lymphomas." (PMID 37152994, 2023). "While UTX mutations are rare in GC B-cell lymphomas, a high incidence of inactivating mutations in the components of COMPASS and its partner HATs, including KMT2D, CREBBP, and EP300, has been reported." (PMID 37198323, 2023). "For example, recent studies demonstrated that somatic inactivating mutations of the histone-acetyltransferase (HAT) domain of CREBBP/EP300 impair its acetyltransferase activity in certain types of non-Hodgkin B-cell lymphoma and bladder cancer." (PMID 32493417, 2020). "Additionally, in the different B-lymphocyte malignant cell lines, the expression levels of BMPR2, EP300, TGFβ2, and TNFAIP3 mRNA were quite different, which may be related to the heterogeneity of B-cell lymphoma." (PMID 25364581, 2014).
gastric cancer (28 papers, 2013 to 2025). A primary or metastatic malignant neoplasm involving the stomach. "EP300-mutated cancers harbored a much higher fraction of microsatellite instable cancers in the colon and gastric cancers." (PMID 34616736, 2021). "In immunohistochemistry analysis, NKX6.3 expression was inversely associated with AICDA expression but positively associated with EP300 expression in 151 gastric cancer tissues." (PMID 30514953, 2018). "Somatic missense alterations of EP300 have been identified in gastrointestinal cancer, such as colorectal and gastric cancer." (PMID 34539736, 2021). "In addition, expression levels of CDH1, CDKN1A, and EP300 were reduced while expression levels of RhoA, ROCK1, ROCK2, PIK3CA, and CCND1 were increased in gastric cancer tissues with reduced or loss of NKX6.3 expression." (PMID 30514953, 2018). "We also found that mRNA expression levels of CDH1, CDKN1A, and EP300 were significantly reduced while those of RhoA, ROCK1, ROCK2, PIK3CA, and CCND1 were significantly increased in gastric cancers with reduced or loss of NKX6.3 expression compared to those in NKX6.3 positive cases." (PMID 30514953, 2018). "These transcription factors play an important role in the progression of GC; for example, EP300 has the ability to regulate the expression of COL1A2 to control the drug resistance of gastric cancer cells to apatinib." (PMID 37735667, 2023). "In recent years, studies have reported the role of EP300 as a tumor‐promoting factor in various cancers, including CRC stomach cancer, and play an important role in the regulation of various biological processes such as activating oncogene, regulation of immune function, and tumor cell growth." (PMID 38872418, 2024). "Results showed that expression levels of NKX6.3, CDH1, CDKN1A, and EP300 were decreased while expression levels of NFκB p65, AICDA, CBFβ, APOBEC3A, APOBEC3B, RhoA, ROCK1, ROCK2, PIK3CA, and CCND1 were increased in CagA positive gastric cancers compared to those in CagA negative cases." (PMID 30514953, 2018).
multiple myeloma (28 papers, 2014 to 2026). "Treatment of myeloma cells with a potent and selective inhibitor of EP300/CBP, CCS1477 (inobrodib), evicted EP300/CBP from the enhancers of genes, inducing differentiation." (PMID 38914477, 2024). "The PROTAC dCBP-1 is based on the CBP/EP300 ligand GNE-781, a recently described CBP/EP300 bromodomain inhibitor that is potent and selective against multiple myeloma cells by abolishing the MYC enhancer." (PMID 37569677, 2023). "A similar mechanism was observed in multiple myeloma cells as well where SP1/EP300 complex promoted proliferation of cancer cells through modulating the transcription of IQGAP1." (PMID 35242497, 2022). "Other studies of CREBBP/EP300 inhibition show similarly modest changes in chromatin accessibility in both multiple myeloma and embryonic stem cells, but this phenomenon has not been observed in hormone-dependent cancers." (PMID 35353838, 2022). "Chetomin exhibited antitumor activity in human myeloma cell lines and primary multiple myeloma cells from patients, suggestive of potential clinical value in multiple myeloma patients characterized by a high EP300 and HIF-1α expression." (PMID 31569621, 2019). "In contrast, our results suggest that CBP/EP300 bromodomain inhibition preferentially targets a more limited subset of hematologic cell lines, with a bias toward multiple myeloma/plasmacytoma cell lines." (PMID 26731516, 2016). "Here, we demonstrate that CBP/EP300 bromodomain inhibition preferentially abrogates the viability of multiple myeloma cell lines." (PMID 26731516, 2016). "In the current study, we demonstrate that CBP/EP300 bromodomain inhibition results in cell cycle arrest and apoptosis in multiple myeloma cell lines." (PMID 26731516, 2016). "Since the regulation of the IRF4 transcriptional axis through small molecule inhibition of CBP/EP300 bromodomains would represent a promising new therapeutic strategy for multiple myeloma, we sought to better understand our initial observations." (PMID 26731516, 2016). "In this regard, specific inhibition of CBP/EP300 bromodomains has been shown to target a more limited subset of hematological malignant cells, with a bias toward multiple myeloma/plasmacytoma cell lines." (PMID 27903272, 2016). "To assess the biological activity of CBP/EP300 bromodomain inhibition, we treated a panel of cell lines of multiple myeloma and acute leukemia origin with SGC-CBP30 and I-CBP112." (PMID 26731516, 2016). "We have shown that CBP/EP300 bromodomain inhibition leads to viability defects in multiple myeloma cell lines and to the suppression of IRF4 and its downstream transcriptional programs in the representative cell line LP-1." (PMID 26731516, 2016). "We first demonstrated by qRT-PCR that IRF4 mRNA was suppressed in a dose-dependent manner by CBP/EP300 bromodomain inhibition in both LP-1 and another multiple myeloma cell line, OPM2." (PMID 26731516, 2016). "Our data suggest that CBP/EP300 bromodomain inhibition exerts its anti-myeloma effects in a mechanism distinct from BET inhibition via the direct transcriptional inhibition of IRF4 and the downstream suppression of IRF4 target genes such as MYC." (PMID 26731516, 2016). "Signal transducer and activator of transcription 3 (STAT3) activation via IL-6 autocrine is associated with LEN-resistance, and bromodomain for CRBN binding protein/E1A binding protein p300 (CBP/EP300) inhibition can release LEN-refractoriness via the STAT3-activated myeloma cell line." (PMID 38004369, 2023).
multiple myeloma (continued). "The activity of CBP/EP300 bromodomain inhibitors in multiple myeloma potentially suggests that this modality may modify similar genes regulated by BET bromodomain inhibitors, but transcriptional profiling does not support this notion." (PMID 26731516, 2016). "We reasoned that CBP/EP300 bromodomain inhibition may exert its phenotypic effects through the suppression of MYC downstream of IRF4 in multiple myeloma cells." (PMID 26731516, 2016). "To better understand the events downstream of IRF4 suppression that are important for reducing proliferation and viability following CBP/EP300 bromodomain inhibition, we reduced the expression of IRF4 in a panel of multiple myeloma cell lines through shRNA transduction." (PMID 26731516, 2016). "While BET proteins are known to similarly target MYC in multiple myeloma, a comparison of CBP/EP300 and BET bromodomain inhibition demonstrated that these modalities target the IRF4-MYC network at different nodes, with BET inhibition having no impact on IRF4 at the doses and timepoints examined." (PMID 26731516, 2016). "Neither CBP nor EP300 have previously been thought of as targets for multiple myeloma therapy." (PMID 26731516, 2016). "Taken together, these data suggest that the bromodomains of CBP and EP300 are involved in the regulation of the IRF4/MYC axis in multiple myeloma cells, and the suppression of the IRF4/MYC axis may be important for the phenotypic effects of CBP/EP300 bromodomain inhibition." (PMID 26731516, 2016). "CBP/EP300 bromodomain inhibition thus targets the IRF4/MYC network, which is critical for multiple myeloma cells independent of the upstream oncogenic signal." (PMID 26731516, 2016).
glioblastoma (25 papers, 2010 to 2026). The most malignant astrocytic tumor (WHO grade IV). "The interaction between SMAD3 and EP300 enhances the expression of mesenchymal markers associated with the mesenchymal subtype of glioblastoma multiforme (GBM)." (PMID 40066091, 2025). "RBBP4 expression is altered in human glioma, and was recently shown to cooperate with the p300 (EP300) histone acetyl transferase to activate DNA repair pathway gene expression in glioblastoma cells in response to temozolomide." (PMID 29914980, 2018). "Importantly, in GBM BCL6 expression can be found associated with defects in apoptosis—for example, BCL6 and the BCL6 target gene EP300 are among anti-apoptosis genes in a signature of survival in primary glioblastoma." (PMID 32320427, 2020). "The method predicts a role for EP300 that was previously unknown in glioblastoma." (PMID 21489305, 2011). "Thus,we hypothesized that expression of EP300 may have value as a new prognostic indicator in glioblastoma." (PMID 21489305, 2011). "Furthermore, the interaction between SMAD3 and EP300 promotes the expression of mesenchymal markers in the mesenchymal subtype of glioblastoma multiforme (GBM)." (PMID 38415253, 2024). "ZDHHC19‐mediated SMAD family member 3 (Smad3) palmitoylation at Cys421 enhances activation of the transforming growth factor (TGF) signaling pathway, and Smad3 interaction with E1A binding protein P300 (EP300) promotes mesenchymal‐like transition in the mesenchymal subtype of glioblastoma (GBM)." (PMID 36018061, 2023). "Since we evidenced in glioblastomas that the amounts of CD44 are high and that the amount of SIRT1 that inactivates EP300 is low, we can assume that this situation may facilitate activation of STAT3 by acetylation." (PMID 21655185, 2011).
viral infection (25 papers, 2012 to 2026). "We next sought to define the potential role for KMT2D and EP300 in viral infection and receptor expression." (PMID 37410700, 2023). "We next directly interrogated the role of KMT2D and EP300 in viral infection." (PMID 37410700, 2023). "We identified EP300, MOV10, RELA, and TRIM25 as top candidates, and more than 60 additional proteins involved in the epigenetic response during viral infection that has therapeutic potential." (PMID 34031419, 2021).
heart failure (24 papers, 2014 to 2025). Inability of the heart to pump blood at an adequate rate to meet tissue metabolic requirements. "For example, EP300 promotes the development of myocyte hypertrophy and represents a pathway that leads to decompensated heart failure." (PMID 36910531, 2023). "MTOR, EP300 and PPP3CC in the Senescence Pathway were also involved in failure of heart." (PMID 32423033, 2020).